HOXA10 (homeobox A10)
Diseases named in the same sentence as HOXA10 in open-access papers (continued):
Sharing a sentence is not in itself a finding about the gene and the disease.
breast carcinoma (continued). "This work is the first to implicate miR-135a down-regulation of HOXA10 expression in breast cancer cell invasiveness." (PMID 22439757, 2012). "It has previously been reported that HOXA9, a paralog of HOXA10, is a tumor suppressor in breast cancer, and expression of HOXD10 in MDA-MB-231 significantly impaired migration." (PMID 22439757, 2012). "HOXA10 is a target gene for miR-135a in breast cancer cells and overexpression of HOXA10 can partially reverse the miR-135a invasive phenotype." (PMID 22439757, 2012). "Our result is in an agreement with a former study that reported HOXA10 expression inhibited matrigel invasion by breast cancer cells." (PMID 22439757, 2012). "Additionally, the modulation of the variable number of tandem repeat (VNTP) domain of the 5-HTT gene was regulated by CTCF, a multifunctional transcription factor that was previously found to regulate the tumor-suppressor activity of HOXA10 in breast cancer." (PMID 36430579, 2022). "In non-small-cell lung carcinoma (NSCLC) and osteosarcoma cells, the central role for miR-124-3p in carcinoma cell invasion and metastasis has been established, while miR-135a enhances metastasis formation in breast cancer by targeting homeobox A10 (HOXA10) protein." (PMID 35628648, 2022). "HOXA9 hypermethylation was also found to be a tool to identify advanced neck squamous cell carcinomas favoring tumor progression and metastasis, predict survival in breast cancer patients, together with HOXA10 hypermethylation, and detect early onset of endometrial cancer." (PMID 32635388, 2020). "On the other hand, HOXA10 gene was considered as a metastatic suppressor in breast cancer." (PMID 30288484, 2018). "HOXA9 and HOXA10 have been reported to be tumor suppressor genes in breast cancer." (PMID 28748001, 2017). "HOXA10 is a transcription factor and has metastasis suppressive function in breast cancer." (PMID 28793339, 2017). "Thus, we suggest that the long-range interplay of HOXA9 and HOXA10 promoter CpGs is an efficient and robust methylation marker for breast cancer." (PMID 28748001, 2017). "Thus, we suggest that the combination of HOXA9 and HOXA10 methylation markers is an independent prognostic marker for breast cancer." (PMID 28748001, 2017). "Therefore, we suggest that the prognostic model using the HOXA9 and HOXA10 promoter CpG combination has translational potential to facilitate determination of breast cancer prognosis and therapeutic strategies targeting a specific molecular regulation module." (PMID 28748001, 2017). "By targeting HOXA10, miR-135a promotes breast cancer cell migration and invasion." (PMID 27539025, 2016). "In addition, miRNA-135a was also found to promote breast cancer cell migration and invasion by targeting HOXA10." (PMID 25888950, 2015). "miRNA-135a promoted breast cancer cell migration and invasion by targeting HOXA10." (PMID 25436889, 2014). "We found HOXA10 was indeed expressed in most breast cancer cell lines except MDA-MB-231." (PMID 22439757, 2012). "We found that over expression of HOXA10 could partially reduce the invasive property mediated by elevated miR-135a levels in the breast cancer cell line BT549." (PMID 22439757, 2012). "In addition, it has been reported that the combination of HOXA9 and HOXA10 promoter CpG islands could predict the survival of breast cancer patients." (PMID 33634306, 2021). "Besides, gastric cancer and breast cancer and some other cancers have close connection with HOXA10." (PMID 34294084, 2021).
breast carcinoma (continued). "Among the genes amplified in the focal regions were a cluster of HOX genes (HOXA7, HOXA9, HOXA10, HOXA11) on 7p15, AKT1 (14q32.33), IGF1R (15q26.3), ERBB2 and NEUROD2 (17q12), all of which have been reported in primary breast cancers." (PMID 24489661, 2014). "HOXA10 mRNA levels were measured by RT-PCR in HEK293, HUVEC, HBL-100 and several breast cancer cell lines." (PMID 22439757, 2012). "In addition, the HOXA1 methylation profile was also considered important in the identification of specific states of cancer progression in lung and breast carcinomas, also in combination with the hypermethylation of other HOX genes such as HOXA10 and HOXB13." (PMID 32635388, 2020). "HOXB13, HOXA10 and HOXA1 genes are hyper-methylated in breast cancer patients." (PMID 33225883, 2020). "It is interesting to mention that four methylation markers (RASGRF1, CPXM1, HOXA10, and DACH1) in circulating cell-free DNA could discriminate cancer from normal with high sensitivity (0.86) and specificity (0.83) in early breast cancer." (PMID 32550045, 2020). "A lack of HOXA10 in breast cancer has been shown to decrease apoptosis and promote metastasis, and thus the role of HOXA10 in the context of palbociclib resistance warrants further investigation." (PMID 32344635, 2020). "By performing 3C PCR assays in MCF7 and MDA-MB-231 breast cancer cells and MCF10A normal breast cells, we confirmed that the HOXA9 and HOXA10 promoters physically interacted each other, while the HOXA11 promoter did not interact with the HOXA9 or HOXA10 promoter." (PMID 28748001, 2017). "In breast cancer, HOXA9 and HOXA10 act as tumor suppressor genes." (PMID 28748001, 2017). "We propose that this gene may function in some breast cancers to suppress migration and invasion rather than HOXA10, and we intend to test this in the near future." (PMID 22439757, 2012). "Our results indicate that miR-135a levels can regulate breast cancer cell migration and invasion, but not proliferation, at least partly through 3'-UTR targeting and repression of HOXA10 expression." (PMID 22439757, 2012).
gastric cancer (23 papers, 2017 to 2025). A primary or metastatic malignant neoplasm involving the stomach. "Principally, HOXA10 is implicated in gastric carcinogenesis due to its activation in gastric cancer." (PMID 33869744, 2021). "The expression of HOXA10 in a specific tissue has been associated with several diseases, including endometrial cancer, prostate cancer, acute myeloid leukemia, gastric cancer, and many other cancers." (PMID 36979165, 2023). "In gastric cancer, the proliferation and invasion of gastric cancer cells are regulated via the promoter hypomethylation and expression of the HOXA10/miR-196b-5p axis." (PMID 36979165, 2023). "It has been reported that HOXA10 deteriorates gastric cancer through inducing Bcl-2 expression and activating JAK1/STAT3 signaling pathway." (PMID 36407869, 2022). "As a member of the HOX family, Homeobox A10 (HOXA10) has been shown to play a notable role in the regulation of various cellular functions in various kinds of diseases and cancers, including gastric cancer, nasopharyngeal carcinoma, and prostate carcinoma." (PMID 33596966, 2021). "Essentially, miR-195 functions as an anti-neoplastic miRNA by regulating the migration and invasiveness of gastric cancer cells in vitro, while HOXA10 has been identified as a target of miR-195." (PMID 33869744, 2021). "We have also identified HOXA10 as the most significantly repressed isoform within the HOXA cluster in EBVaGC patients, gastric cancer and lymphoma cell lines, we therefore decided to evaluate the antiviral potential of HOXA10 against EBV." (PMID 32841292, 2020). "In gastric cancer, HOXA10 is one of the most significant DNA methylation markers, but contradictorily it seems required for cell proliferation." (PMID 32841292, 2020). "In gastrointestinal tumors, miR-4429 has been reported to reduce METTL3 expression in gastric cancer, and another study reported that HOXA10 increases Smad2/3 expression in the nucleus and promotes METTL3 deposition to regulate the progression of EMT in gastric cancer." (PMID 38166703, 2024). "For instance, HOXA10 promotes gastric cancer EMT via the TGFB2/Smad/METTL3 signaling axis." (PMID 38178023, 2024). "A previous study reported that EMT induced by HOXA10 contributed to gastric cancer metastasis." (PMID 35519620, 2022). "The direct contribution of HOXA10 to gastric cancer needs to be further clarified." (PMID 32841292, 2020). "Hoxa10, a member of the homeobox gene family, can participate in the development and growth of multiple systems, as indicated by its critical roles in male and female fertility, liver tumorigenesis, gastric cancer invasion, and leukemogenesis." (PMID 32427900, 2020). "However, in several solid tumors, i.e. oral and gastric cancer, miR-494-3p acts as an anti-oncogene by targeting HOXA10 and c-MYC respectively." (PMID 28533480, 2017). "Moreover, HOXA10 can promote proliferation and inhibit apoptosis of gastric cancer cells." (PMID 36407869, 2022). "We previously demonstrated that HOXA10 was significantly upregulated in gastric cancer (GC) and promoted GC cell proliferation." (PMID 33563300, 2021). "Additionally, HOXA10 might promote cell proliferation by elevating Bcl-2 expression and inhibiting apoptosis in gastric cancer, and high expression of HOXA10 predicted poor overall survival in gastric cancer patients." (PMID 32296636, 2020). "Homeobox A10 (HOXA10) has been implicated critical for the promotion of carcinogenesis, but the underlying mechanism between HOXA10 and malignant gastric cancer (GC) phenotype remains elusive." (PMID 31364281, 2019). "For instance, miR-135a-5p promoted the progression of head and neck squamous cell carcinoma by targeting HOXA10, the progression of thyroid carcinoma by VCAN, and the progression of gastric cancer by KIFC1." (PMID 32010197, 2019). "Interestingly, homeobox A10 (HOXA10) upregulation increases m6A levels and METTL3 expression in gastric cancer, possibly by promoting the TGFB2/SMAD pathway." (PMID 40986143, 2025).
gastric cancer (continued). "Recent results obtained in human gastric cancer cells (AGS and MKN28) have revealed that inhibition of SF3B1 reduced their proliferation rate by inducing apoptosis and G2/M phase arrest through altering homeobox A10 (HOXA10) mRNA splicing." (PMID 35008179, 2021). "Also, LINC01089 is found to be a lncRNA playing tumor-suppressive role in gastric cancer via regulating miR-27a-3p/TET1 axis and can block the proliferation as well as metastasis of colorectal cancer cells through the regulation of miR-27b-3p/HOXA10 axis." (PMID 34281560, 2021). "In summary, we demonstrated that expression of HOXA10 and BCL2 was significantly upregulated in gastric cancer (GC) tissues." (PMID 31364281, 2019).
ovarian carcinoma (20 papers, 2010 to 2024). A malignant neoplasm originating from the surface ovarian epithelium. "The association between HOXA10 and endometroid epithelial ovarian cancer was confirmed in a further study from a different group, who also showed repression of HOXA10 transcription through Wilms tumour 1 (WT1) binding to a repressor site." (PMID 31382546, 2019). "In conclusion, the serum exosomal DIO3OS-hsa-miR-27a-3p-HOXA10 competitive endogenous mechanism signaling axis affects ovarian cancer development and disease survival by targeting dysregulated transcriptional pathways in cancer." (PMID 35910206, 2022). "In ovarian cancer miRNA‐665 suppresses the growth and migration of cancer cells by negatively regulating Homeobox Protein Hox-A10 (HOXA10)." (PMID 34889712, 2021). "Our previous studies have determined the critical role of HOXA10 in ovarian cancer, and we have been exploring the role of HOXA10 in female malignancies for a long time." (PMID 34496932, 2021). "For instance, miR-135a acts as a suppressor of epithelial ovarian cancer by downregulating homeobox A10 (HOXA10) expression." (PMID 32710726, 2020). "Several studies have shown that HOXA10 can increase the growth and invasion of ovarian cancer cells, and that endometroid, clear cell and mucinous tumours (but not serous) express significantly higher levels of HOXA10 compared with normal ovarian tissue." (PMID 31382546, 2019). "In other study conducted to examine the role of miR-135a tumor suppressor in epithelial tissue of the patients with ovarian cancer, it was found that HOXA10 gene was targeted by miR-135a." (PMID 30288484, 2018). "HOXA10 is involved in gene expression, regulation, morphogenesis, and differentiation in ovarian carcinoma." (PMID 29914539, 2018). "Further, they concluded that the expression of miR-135a significantly decreased in epithelial tissue of ovarian cancer, with a higher expression of HOXA10 in contrast." (PMID 30288484, 2018). "Specifically, upregulation of HOXA10 and HOXB3 genes and downregulation of HOXC5 were significantly associated with unfavorable survival outcomes in patients with ovarian cancer." (PMID 29050303, 2017). "In conclusion, dysregulated expression of the HOXA10, HOXB3, and HOXC5 genes was significantly associated with favorable or unfavorable overall survival in a large ovarian cancer cohort from TCGA." (PMID 29050303, 2017). "A more recent study has shown that increased expression of HOXA10 is present in ovarian carcinomas as a result of promoter hypomethylation of HOXA10." (PMID 21906307, 2011). "Moreover, upregulated expression of HOXA10 was shown to promote epithelial mesenchymal transition as well as proliferation, migration and invasion of ovarian cancer cells and decrease patient survival." (PMID 35910206, 2022). "In ovarian cancer, miR-135a inhibits the growth and survival of cancer cells by repressing HOXA10." (PMID 28415713, 2017). "Homeobox A10 (HOXA10) and Homeobox A11 (HOXA11) have previously been shown to be overexpressed in ovarian cancers, and play a role in stimulating tumor growth and determining the histologic identity of epithelial ovarian cancers." (PMID 22371431, 2012). "There is clear evidence for this in ovarian cancer where the expression of HOXA9, HOXA10 or HOXA11 confer a serous, endometrioid-like and mucinous-like phenotype respectively." (PMID 20219106, 2010).
adenomyosis (19 papers, 2012 to 2025). The growth of endometrial tissue inside the muscular wall of the uterine corpus. "Furthermore, lower implantation success rates are associated with lower HOXA10 expression in adenomyosis." (PMID 40305321, 2025). "Numerous gynecological conditions that affect the uterus, including adenomyosis, polyps, fibroids, and leiomyomas, have changed HOXA10 expression." (PMID 40305321, 2025). "HOXA10 expression is decreased in stromal cells and endometrial tissue in patients with adenomyosis, which hinders decidualization in vitro." (PMID 40305321, 2025). "Multiple regression analysis confirmed that adenomyosis significantly affected the stromal HOXA10 expression when looking at age, menstrual cycle phase and concurrent presence of leiomyomas." (PMID 39274229, 2024). "HOXA10 expression was decreased in adenomyosis during the secretory phase, and also the proliferative phase, where it reached statistical significance in both epithelial and stromal compartments." (PMID 39274229, 2024). "In this study, differential HOXA10 expression was observed between adenomyosis and control patients in both epithelial and stromal tissues." (PMID 39274229, 2024). "In the epithelium, HOXA10 expression was intense in healthy endometrium from the proliferative phase, significantly stronger than that from adenomyosis patients in the same cycle phase (p = 0.0198)." (PMID 39274229, 2024). "In the stromal compartment, HOXA10 expression remained low during both the proliferative and secretory phases in adenomyosis and was significantly different from the corresponding phases in healthy controls (p = 0.0205; 0.0198)." (PMID 39274229, 2024). "Within the uteri of mice with adenomyosis, reduced expression of the progesterone receptor and a decreased expression of two implantation-related markers (HoxA10 and integrin β3) were observed." (PMID 38451875, 2024). "Previous studies demonstrated that the downregulation of HOXA10 in the endometrium was related to impaired endometrial receptivity in patients with adenomyosis." (PMID 35937844, 2022). "After combined administration of GnRHa and CCL21 in the uterus of mice with adenomyosis, expression of the endometrial receptivity marker HOXA10 was significantly increased." (PMID 35022045, 2022). "Previous studies also found that HOXA10 expression was downregulated in the endometria of patients with adenomyosis, which led to impaired endometrial receptivity." (PMID 35937844, 2022). "Our results indicate that when CCL21 and GnRHa were combined to treat mice with adenomyosis, they enhanced the expression of HOXA10 to promote endometrial receptivity." (PMID 35022045, 2022). "Consistently, the positive relationship between IL33 and HOXA10 expression in the endometrium was verified in the analysis of adenomyosis mouse model." (PMID 35937844, 2022). "The expression levels of HOXA10 and IL-10 in the adenomyosis group were significantly lower than those in the control group, and there was a positive correlation between HOXA10 and IL-10 protein levels in all the women examined." (PMID 30687738, 2018). "The aim of this study was to investigate the potential role of IL-10 in regulating the receptivity marker HOXA10 in the endometrium of women with adenomyosis." (PMID 30687738, 2018). "The endometrial HOXA10 protein level was severely decreased (by approximately 50%) in women with adenomyosis compared with that in normal controls (P < 0.001)." (PMID 30687738, 2018). "In this study, we aimed to characterize the molecular changes in IL-10 and HOXA10 in the endometrium in relation to subfertility in women with adenomyosis and to explore the potential regulatory relationship between these characteristics." (PMID 30687738, 2018). "Both IL-10 and HOXA10 levels in the endometrium are significantly reduced in women with adenomyosis compared with those in control women." (PMID 30687738, 2018).